LAMA1 (laminin subunit alpha 1)
Description:
Binding to cells via a high affinity receptor, laminin is thought to mediate the attachment, migration and organization of cells into tissues during embryonic development by interacting with other extracellular matrix components. As a ligand for alpha-dystroglycan, it is involved in a number of processes including epithelium branching morphogenesis, down-regulation of apoptotic signals in muscle via the activation of PI3K/AKT signaling, and activation of RAC1 signaling. As a subunit of laminin-1 (also known as laminin-111 or EHS laminin), it is involved in the stimulation of agrin-induced receptor clustering through a MuSK-independent pathway.
Synonyms: LAMA; PTBHS; S-LAM-alpha
Tractability: Antibody: its Gene Ontology location is reachable by antibodies, with high confidence; UniProt places it where antibodies can reach, with medium confidence; UniProt predicts a signal peptide or a membrane-spanning region. PROTAC: ubiquitination databases record sites on it. Other modalities: an approved drug acts on it.
Target class: Structural protein
Gene: Protein-coding gene on chromosome 18 (6,941,742 to 7,117,859, reverse strand). Ensembl gene ENSG00000101680.
Subcellular location: Secreted, extracellular space, extracellular matrix, basement membrane
Pathways (Reactome):
Extracellular matrix organization: ECM proteoglycans; Formation of the dystrophin-glycoprotein complex (DGC); Laminin interactions; Non-integrin membrane-ECM interactions
Developmental Biology: Developmental Lineage of Pancreatic Ductal Cells; L1CAM interactions
Disease: Attachment of bacteria to epithelial cells
Signal Transduction: MET activates PTK2 signaling
Gene Ontology:
Molecular function: protein binding; extracellular matrix structural constituent; receptor ligand activity; glycosphingolipid binding; signaling receptor binding
Biological process: cell surface receptor signaling pathway; negative regulation of muscle cell apoptotic process; nervous system development; positive regulation of cell adhesion; positive regulation of integrin-mediated signaling pathway; positive regulation of muscle cell differentiation; positive regulation of phosphatidylinositol 3-kinase/protein kinase B signal transduction; positive regulation of Rac protein signal transduction; positive regulation of skeletal muscle acetylcholine-gated channel clustering; regulation of basement membrane organization; signal transduction; cell adhesion; regulation of cell adhesion; regulation of cell migration; regulation of embryonic development
Cellular component: basement membrane; extracellular matrix; extracellular region; laminin-1 complex; laminin-3 complex; membrane; plasma membrane; protein complex involved in cell-matrix adhesion; synapse; cell-cell junction; laminin complex
Genetic constraint (gnomAD): Loss-of-function variants: 199 observed, 332.72 expected, observed/expected ratio (o/e) 0.6, 90% interval 0.53 to 0.67. The upper end of that interval is the gene's LOEUF score, 0.67, which puts it in group 2 of 6, group 1 being the genes least tolerant of losing a copy. Missense variants: 3,648 observed, 3,953.3 expected, observed/expected ratio (o/e) 0.92, 90% interval 0.9 to 0.95. Synonymous variants: 1,471 observed, 1,529 expected, observed/expected ratio (o/e) 0.96, 90% interval 0.92 to 1.
Homologues: Orthologues: chimpanzee LAMA1 (99% identical), dog LAMA1 (81% identical), rabbit LAMA1 (79% identical), pig LAMA1 (78% identical), rat Lama1 (77% identical), mouse Lama1 (76% identical), guinea pig LAMA1 (71% identical), tropical clawed frog lama1 (61% identical), zebrafish lama1 (52% identical). Paralogues in human: LAMA2 (46% identical), LAMA3 (25% identical), LAMA5 (24% identical), HSPG2 (18% identical), USH2A (15% identical), LAMB1 (13% identical), LAMB2 (13% identical), AGRN (13% identical), LAMB4 (13% identical), LAMC1 (13% identical), LAMC3 (12% identical), LAMA4 (12% identical), and 15 more.
Diseases named in the same sentence as LAMA1 in open-access papers:
LAMA1 is named in the same sentence as 98 diseases in open-access papers, as found by Europe PMC text mining. Sharing a sentence is not in itself a finding about the gene and the disease. The quoted sentences say what the papers report.
myopia (12 papers, 2006 to 2025). "Protein-truncating variants in the LAMA1 gene have been linked to congenital muscular dystrophy, myopia, and retinal dystrophy." (PMID 28771244, 2018). "In the high myopia group (n=74), LAMA1 gene analysis revealed heterozygous mutations in 34 patients (45.9%), homozygous mutations in 25 (33.8%), and no mutations in 15 patients (20.3%)." (PMID 29805427, 2018). "Here, to further investigate the correlation between LAMA1 and high myopia, we conducted a case-control study to analyze the SNPs of LAMA1 for association with high myopia." (PMID 21541277, 2011). "The purpose of this study was to determine if high myopia is associated with single nucleotide polymorphism (SNP) variants in LAMA1 in Chinese subjects." (PMID 21541277, 2011). "LAMA1 encodes one of the alpha 1 subunits of laminin, and biallelic pathogenic variants in this gene cause Poretti–Boltshauser syndrome, a disorder associated with high myopia and variable retinal dystrophy." (PMID 41153400, 2025). "For example, the LAMA1 gene is associated with autosomal recessive Poretti-Boltshauser syndrome, characterized by cerebellar dysplasia, myopia, variable retinal dystrophy and eye movement abnormalities ataxia, delayed motor development, language impairment and intellectual disability." (PMID 33407854, 2021). "Our study found that early onset high myopia with midline alopecia areata could be caused not only by mutations of the COL18A1 gene but also by mutations in the LAMA1 gene." (PMID 34249907, 2021). "However, one of its activation targets, LAMA1, has been found to cause myopia in the presence of other phenotypes." (PMID 30704416, 2019). "Our results indicate that the polymorphism of rs2089760, located in the promoter region of LAMA1, may be associated with high myopia in the Chinese population and should be investigated further." (PMID 21541277, 2011). "In conclusion, our results indicate that the polymorphism of rs2089760, located in the promoter region of LAMA1, may be associated with high myopia in Chinese population and should be investigated further." (PMID 21541277, 2011). "Finally, another study identified five single-nucleotide polymorphisms (SNPs) in the LAMA1 gene among 97 Chinese individuals diagnosed with high myopia, providing additional evidence to support an association between variants in LAMA1 and high myopia." (PMID 41153400, 2025). "Similarly, the LAMA1 rs2089760 G > A mutation was reported to reduce transcription factor binding ability and transcription initiation activity and negatively control the gene transcription of LAMA1, playing a crucial role in pathological myopia." (PMID 36824663, 2023). "Numerous studies have investigated the role of TGFB1 and LAMA1, which are involved in the restructuring of scleral collagen and proteoglycans, in myopia." (PMID 29805427, 2018). "LAMA1 (alpha subunit of laminin) is a promising candidate gene for high myopia present in the MYP2 (myopia 2) region." (PMID 21541277, 2011). "Furthermore, it is known that patients with bi-allelic pathogenic variants in LAMA1 (causing Poretti–Boltshauser syndrome, OMIM #615960) develop high myopia as one of the symptoms." (PMID 36737489, 2023). "In the present study we evaluated polymorphisms in the LAMA1 (rs2089760) and TGFB1 (rs4803455) genes in children younger than 13 years of age with <6 D myopia in an attempt to further elucidate the genetic basis of high myopia." (PMID 29805427, 2018). "In humans, LAMA1 maps to the 18p11.31 region that contains a gene for high-grade myopia (MYP2;)." (PMID 16522196, 2006). "Interestingly, the severity of myopia did not correlate with specific LAMA1 variants, highlighting the possibility of additional modifying influences." (PMID 40428839, 2025).
Cerebellar dysplasia (9 papers, 2015 to 2025). Cerebellar dysplasia (abnormal growth or development) is defined by abnormal cerebellar foliation, white matter arborization, and gray-white matter junction. "The combination of cerebellar dysplasia with cysts, enlarged rhomboid-shaped fourth ventricle, and splayed superior cerebellar peduncles should prompt genetic testing for LAMA1 variants." (PMID 41426793, 2025). "Lastly, LAMA1 (duplicated region on chromosome 18), laminin involved in cell adhesion and axon outgrowth during embryonic development is associated with cerebellar dysplasia and ID in individuals with homozygous variants." (PMID 33922640, 2021). "Diseases associated with LAMA1 include the Poretti-Boltshauser syndrome and cerebellar dysplasia with cysts." (PMID 32213190, 2020). "In α-dystroglycanopathies, GPR56-related polymicrogyria, and Poretti-Boltshauser syndrome due to LAMA1 mutations, cerebellar dysplasia is typically associated with cerebellar cysts." (PMID 26331051, 2015). "A mutation in LAMA1 (laminin subunit alpha 1) causes cerebellar dysplasia with retinal dystrophy." (PMID 33917666, 2021). "In addition, efforts to re-analyse unsolved Joubert syndrome-like patients and those with cerebellar dysplasia and cysts should be made by opening up virtual gene panels to other genetic phenocopies, such as LAMA1." (PMID 34423300, 2021). "Global cerebellar dysplasia has been reported in a few posterior fossa malformations including Chudley-McCullough syndrome, α-dystroglycanopathies, GPR56-related polymicrogyria, and Poretti-Boltshauser syndrome due to LAMA1 mutations." (PMID 26331051, 2015).
Poretti-Boltshauser syndrome (8 papers, 2015 to 2025). "In the genetic clinic, a genetic test was done for both sisters, which revealed a mutation in the LAMA1 gene that confirmed the diagnosis of a rare genetic disorder called Poretti-Boltshauser syndrome." (PMID 39925523, 2025). "Poretti-Boltshauser syndrome (PTBHS) is a neuro-ophthalmological rare genetic disease that has an autosomal recessive inheritance that occurs as a consequence of a mutation in the LAMA1 gene." (PMID 39925523, 2025). "Patient #7 showed characteristic features of Poretti-Boltshauser syndrome (PTBHS) on neuroimaging, and detection of a homozygous pathogenic variant in LAMA1 confirmed this diagnosis." (PMID 37131188, 2023).
breast cancer (7 papers, 2018 to 2024). A primary or metastatic malignant neoplasm involving the breast. "Notably, unique metastatic biomarkers found in mFMC, such as POU5F1 (OCT4) and LAMA1, have been identified in human breast cancer." (PMID 38951817, 2024). "Taken together, the results on OPG and LAMA1 function suggest that they respectively promote protection from TRAIL-induced apoptosis and adhesion-mediated survival of breast cancer cells." (PMID 35469015, 2022). "To analyze the functional role of LAMA1, we plated breast cancer cells onto surfaces coated with LN111 or LN121, the only laminin trimers containing the α-chain transcribed by LAMA1." (PMID 35469015, 2022). "We have previously examined three laminin subunit genes (LAMA1, LAMA2, and LAMB1), the promoter regions of which undergo abnormal methylation in breast cancer (BC) at frequencies higher than 16%5." (PMID 33500458, 2021). "Most importantly, 5 genes were found to be associated with all of the most highly enriched GO terms and KEGG pathways: WNT5A, WNT6, WNT11, WNT5B and LAMA1, which suggested that WNTs may be essential targets of ATBF1 and may contribute to breast cancer tumorigenesis." (PMID 36476423, 2022). "The sphere-forming ability of breast cancer cells was markedly increased when treated with CM containing INHBB or SCGB3A1, but not with OPG or LAMA1." (PMID 35469015, 2022).
Intellectual disability (4 papers, 2019 to 2024). "Out of 8459 probands recruited in GEL with human phenotype ontology terms ‘intellectual disability’ and/or ‘developmental delay’, 18 cases (0.2%) were molecularly solved for Joubert syndrome genes versus only two cases solved with LAMA1 variants." (PMID 34423300, 2021). "We advocate the inclusion of LAMA1 genetic analysis on all intellectual disability and Joubert syndrome gene panels and promote a wider awareness of the clinical and radiological features of these syndromes." (PMID 34423300, 2021). "It is the first time to report variants in EFNB1, NAA10, DHCR7, LAMA1 and NFIX in Chinese intellectual disability/developmental delay patients and first report about variants in NAA10 and LAMA1 in affected individuals of Asian ancestry." (PMID 31088393, 2019).
type 2 diabetes (4 papers, 2012 to 2024). "For example, APP interacts with susceptibility genes to type 2 diabetes (LAMA1 and IDE) and genes associated with Parkinson's disease risk including SNCA and MAPT." (PMID 24376773, 2013). "The LAMA1 type 2 diabetes risk allele was associated with lower BMI within cases alone (P = 2×10−6 when analysing BMI as a quantitative trait in 26,366 cases), a result consistent with its association being stronger in the lean case analysis." (PMID 22693455, 2012). "In the lean case analysis, the LAMA1 variant was associated with type 2 diabetes (combined P = 8.4×10−9, OR = 1.13 [1.09–1.18], total lean cases N = 4,993, controls = 70,515) compared to an OR = 1.03 [1.00–1.06] in the obese case analysis." (PMID 22693455, 2012). "A variant (rs8090011) in the LAMA1 gene was associated with type 2 diabetes in lean cases (P = 8.4×10−9, OR = 1.13 [95% CI 1.09–1.18]), and this association was stronger than that in obese cases (P = 0.04, OR = 1.03 [95% CI 1.00–1.06])." (PMID 22693455, 2012). "Similarly, LAMA1 is implicated in dementia, providing a compelling rationale to interrogate its correlation with type 2 diabetes." (PMID 38790243, 2024). "BMI stratified analysis for the association of rs8090011 in LAMA1 with type 2 diabetes." (PMID 25951451, 2015). "In addition, the LAMA1 type 2 diabetes risk allele was associated with lower BMI within cases alone (P = 2×10−6 when testing BMI as a quantitative trait in cases) – a similar result was previously reported for the TCF7L2 risk allele." (PMID 22693455, 2012). "The enrichment of the LAMA1 signal in lean type 2 diabetes cases compared to obese cases is likely to be a real effect but the enrichment of the HMG20A signal in obese cases is more likely to be due to chance." (PMID 22693455, 2012). "We next attempted to understand further the associations between SNPs in the LAMA1 and HMG20A loci and lean and obese type 2 diabetes cases respectively." (PMID 22693455, 2012). "We also performed BMI-stratified analyses using cutoff value of 30 kg/m2, but did not observe any association of rs8090011 in LAMA1 with type 2 diabetes." (PMID 25951451, 2015). "In BMI-stratified analyses, we did not observe any association of rs8090011 in LAMA1 with type 2 diabetes (p ≥ 0.05, adjusted for sex, age and BMI)." (PMID 25951451, 2015). "The LAMA1 locus has been shown to be associated with lean type 2 diabetes, but not with obese type 2 diabetes, in the European GWAS." (PMID 25951451, 2015). "Moreover, rs8090011 in the laminin alpha-1 gene (LAMA1) has been shown to be associated with non-obese European type 2 diabetes." (PMID 25951451, 2015). "By stratifying type 2 diabetes into two well accepted definitions of lean and obese cases, we identified and replicated one locus in each BMI stratum, each previously unreported in European studies: a signal in the LAMA1 gene in the lean stratum and a signal in the HMG20A gene in the obese stratum." (PMID 22693455, 2012). "In conclusion, we report associations with the LAMA1 and HMG20A (not previously associated at genome-wide significance in Europeans) gene regions with type 2 diabetes risk." (PMID 22693455, 2012).
adenoma (3 papers, 2021 to 2023). A neoplasm arising from the epithelium. "New mutations were found in OR1B1 (GPCR signaling pathway) in adenoma evolution, and LAMA1 (PI3K-Akt signaling pathway) and ADCY3 (FGFR signaling pathway) in CRC evolution." (PMID 35785171, 2022). "These new driver mutations in OR1B1 (GPCR signaling), LAMA1 (PI3K-Akt signal in CRC evolution), and ADCY3 (FGFR signaling) of adenoma evolution and cancer evolution, confirming that both colorectal adenomas and CRC were of monoclonal origin." (PMID 35785171, 2022). "New driver mutations were identified that developed during the evolution of both adenoma and cancer: on one hand OR1B1 (GPCR signaling pathway) was related to adenoma evolution; on the other hand, LAMA1 (PI3K-Akt signaling pathway) and ADCY3 (FGFR signaling pathway) had a role in CRC evolution." (PMID 34833475, 2021).
colorectal cancer (3 papers, 2014 to 2023). A primary or metastatic malignant neoplasm that affects the colon or rectum. "Consistent with our findings, LAMA1 is frequently upregulated in multiple cancers, including colorectal carcinoma, melanoma, gastric cancer, and ESCC, and plays a crucial role in tumor metastasis." (PMID 34226522, 2021).
esophageal cancer (3 papers, 2021 to 2023). A primary or metastatic malignant neoplasm involving the esophagus. "Through multicenter large-sample case-control research, we aim to thoroughly investigate the association between LAMA1 single-nucleotide polymorphisms and the incidence and progression of esophageal cancer." (PMID 36824663, 2023). "In conclusion, we found a strong association of LAMA1 rs62081531, rs539713, rs566655, and rs607230 polymorphisms with esophageal cancer susceptibility in the Chinese population." (PMID 36824663, 2023). "Due to the single-nucleotide polymorphism of LAMA1, the mutated site seems unable to effectively translate LAMA1 into laminin subunit α1 so as to exert its specific biological function, hence preventing esophageal cancer susceptibility." (PMID 36824663, 2023). "LAMA1 SNPs may significantly impact the occurrence of esophageal cancer and may serve as effective diagnostic biomarkers." (PMID 36824663, 2023). "LAMA1 SNPs may have a significant impact on the occurrence of esophageal cancer and may serve as potential diagnostic biomarkers." (PMID 36824663, 2023). "In our study, LAMA1 mutation showed protective factors in both rs62081531 G > A and rs607230 T > C, and basic research also found that LAMA1 deficiency could inhibit the proliferation and invasion of esophageal cancer." (PMID 36824663, 2023). "How these SNPs of LAMA1 translate into biological function in the evolution of esophageal carcinoma is definitely a primary subject of our future investigation, which is currently technically difficult due to the lack of biological tools in our lab." (PMID 36824663, 2023). "However, there are few reports on LAMA1 and esophageal cancer." (PMID 36824663, 2023). "Circular RNA hsa_circ_0000277 sequesters miR-4766-5p to upregulate laminin subunit alpha 1 (LAMA1) and promote esophageal carcinoma progression." (PMID 36609391, 2023).
liver fibrosis (3 papers, 2021 to 2024). "The higher quantities of COL1A1, Lama1, and Timp1 proteins were expressed in the model group, which were considerably subdued by PC administration, signifying that PC reduced CCl4-induced liver fibrosis." (PMID 35721129, 2022). "In addition, the Lamb1 and Lama1 genes are related to the progression of liver fibrosis." (PMID 39591294, 2024). "Then, the effect of PC on liver fibrosis was further examined by identifying the characteristic indicators of liver fibrosis, including COL1A1, Lama1, and Timp1." (PMID 35721129, 2022).
melanoma (3 papers, 2021 to 2023). A malignant, usually aggressive tumor composed of atypical, neoplastic melanocytes. "Several of the EMT-related genes with higher expression in NR patients encoded for molecules controlling adhesion (ITGB3, VCAM1, collagens, and others), interaction with extracellular matrix (VEGFA, MMP14, WNT5A, LAMA1, and others), and melanoma de-differentiation (KRT9, KRT10, EGFR, and others)." (PMID 37739939, 2023).